TLR7 (toll like receptor 7)
Diseases named in the same sentence as TLR7 in open-access papers (continued):
Sharing a sentence is not in itself a finding about the gene and the disease.
inflammation (8 papers, 2012 to 2023). Aberrant reaction of the microcirculation characterized by movement of fluid and leukocytes from the blood into extravascular tissues. "Duplication of Tlr7 in males overrides the sex-bias and triggers severe immunopathology marked by intense lung inflammation and early mortality." (PMID 34376664, 2021). "Here, we established that small RNAs trigger age‐related renal inflammation via TLR7 signaling pathway." (PMID 28665028, 2017). "In RA, hyperactivated macrophages increased the expression of toll-like receptors (TLRs), such as TLR2, TLR3, TLR4, and TLR7, which induce synovial inflammation and cartilage destruction by releasing chemokines, pro-inflammatory cytokines, and degradative enzymes have been recognized." (PMID 36172378, 2022). "Importantly, asthmatics with an eosinophilic airways inflammation, as determined by bronchial lavage, displayed significantly reduced TLR7 and IFNλ2/3 expression, independent of atopic status." (PMID 26108570, 2015). "Somewhat surprisingly, CS-induced pulmonary inflammation in BALF and tissues and histopathology scores were not altered in Tlr7−/− mice." (PMID 37963864, 2023).
neurodegenerative disease (8 papers, 2018 to 2024). A disorder of the central nervous system characterized by gradual and progressive loss of neural tissue and neurologic function. "Subsequent studies validated our initial hypothesis that endogenous miRNAs, such as let-7b, are released from injured neurons, stimulate TLR7, thereby sending a danger signal to neighboring neurons, and cause further spread of CNS damage, particularly in the setting of neurodegenerative diseases." (PMID 34589086, 2021). "Further studies have to be performed to elucidate the function of TLR7 in autophagy and its impact in neurodegenerative diseases." (PMID 30333729, 2018). "Given the involvement of TLR signaling in multiple neurodegenerative diseases, let-7/TLR7/TRAIL signaling may represent a fundamental mechanism for neurodegeneration linked to neuroimmune activation that could be targeted therapeutically." (PMID 33806288, 2021). "In accordance with this, we hypothesize on a functional contribution of TLR signaling to MS and other neurodegenerative diseases mediated by miR-132-5p, acting in its extracellular state as a signaling molecule for TLR7/8." (PMID 31940779, 2020). "At present, the role of microglial TLR7 in neurodegenerative diseases remains elusive." (PMID 30333729, 2018). "Finally, future studies may focus on therapeutic interventions that could modulate miR-154-5p levels or block its interaction with TLR7/8 in neurodegenerative disease." (PMID 38474371, 2024). "However, as TLR7 also has the capability to detect endogenous ssRNA such as microRNAs (miRNAs), it is plausible that TLR7 activation via miRNAs may influence inflammation in neurodegenerative disease." (PMID 38474371, 2024).
Neurological Disease (7 papers, 2015 to 2025). "Damage-associated molecular patterns (DAMPs), such as nucleic acids from apoptotic cells or secreted micro-RNAs, have also been associated with neurological disease or damage and can also stimulate PRRs, particularly endosomal toll-like receptor 7 (TLR7) and TLR9." (PMID 26214311, 2015). "Mechanically, the role of TLR7 in sex differences of neurological disorders is interpreted by its function to demyelination during aging." (PMID 40191607, 2025). "In infectious contexts, TLR7 plays multiple roles relevant to neurological disorders and inflammatory responses in the CNS." (PMID 31730654, 2019). "When simian immunodeficiency virus (SIV) infects the brains of rhesus macaques, the secretion of microRNA21 activates the TLR7 pathway, leading to neurological disease." (PMID 31730654, 2019). "Since recent studies indicate that TLR7 recognizes not only viral RNA but also microRNAs that are released by damaged neurons and elevated during neurological diseases, we first examined the response of glial cells to TLR7 stimulation using microarray analysis." (PMID 26214311, 2015). "This underscores the importance of studying TLR7 and TLR8 in human experimental models within the context of neurological disease." (PMID 41322409, 2025).
adenocarcinoma (4 papers, 2020 to 2022). A common cancer characterized by the presence of malignant glandular cells. "Concerning SCD4, high Toll-like receptor 7 expression is associated with the overexpression of SDC4 in patients with adenocarcinoma, which suggests that its expression is related to metastasis." (PMID 32503508, 2020).
heart disease (3 papers, 2017 to 2025). "Therefore, it is likely that fibroblasts significantly contribute to the increased expression of TLR1, TLR3, and TLR7 and their downstream signaling pathways we previously observed in the myocardium of patients with cardiac disease." (PMID 39828779, 2025).
hematological malignancies (3 papers, 2021 to 2024). "The majority of clinical trials using TLR agonists to treat hematological malignancies have focused on TLR3, TLR7/8, and TLR9." (PMID 36476317, 2022).
hematological cancer (2 papers, 2021 to 2022). "The TLR7 agonist 852A has been studied in a phase II trial in patients with recurrent malignant hematologic tumors." (PMID 36476317, 2022).
metabolic disease (1 paper, 2019). A congenital disorder (due to inherited enzyme abnormality) or acquired (due to failure of a metabolically important organ) disorder resulting from an abnormal metabolic process. "Hence, TLR7 signaling is implicated in the connection between SLE and metabolic disease." (PMID 31552019, 2019). "Our study uncovers the implication of TLR7 signaling in the interconnection of SLE and metabolic abnormalities, indicating that TLR7 might be a novel approach as a tailored therapy in SLE and metabolic diseases." (PMID 31552019, 2019).
psychiatric disorder (1 paper, 2022). A disorder characterized by behavioral and/or psychological abnormalities, often accompanied by physical symptoms. "Considerable evidence suggests that type I IFN is associated with psychiatric disorders, and that the production of type I IFNs as a result of TLR4 induced IRF3 activation and TLR7 induced IRF7 activation may be closely associated with IFN-mediated psychiatric disorders." (PMID 36325336, 2022).
TLR7 also shares sentences with these, for which no sentence is quoted: viral diseases (8 papers); atopic dermatitis (4); ischemic stroke (4); primary immunodeficiency (4); colorectal (3); Encephalopathy (3); Parkinson disease (3); rhinitis (3); acute respiratory distress syndrome (2); aspergillosis (2); benign neoplasm (2); Bowen’s disease (2); candidiasis (2); chronic pancreatitis (2); cryptococcosis (2); cutaneous squamous cell carcinoma (2); dilated cardiomyopathy (2); fibrosis (2); keratosis (2); metastatic melanoma (2); mycoses (2); neurotoxicity (2); paracoccidioidomycosis (2); pericardial effusion (2); pustular psoriasis (2); respiratory diseases (2); rheumatic (2); stomach cancer (2); systemic sclerosis (2); ulcerative colitis (2).
A further 124 diseases each share a sentence with TLR7 in 1 paper.